BRCA2 (BRCA2 DNA repair associated)
Diseases named in the same sentence as BRCA2 in open-access papers (continued):
Sharing a sentence is not in itself a finding about the gene and the disease.
breast cancer (continued). "A total of 568 breast cancer cases occurred in first-degree relatives, with an incidence of 21.3%, 20.4, and 8.4% for BRCA1, BRCA2 and non-carrier families, respectively." (PMID 29861850, 2018). "We used breast cancer cell lines HCC1937 (BRCA1−/−) and MDAMB231 (BRCA+/+) as controls and HeLa cell lines silenced or not for BRCA1 and BRCA2." (PMID 23761435, 2013). "If the first breast cancer was diagnosed at the age of 50 or later, 25-year cumulative risks were 21.6% for BRCA1, 15.5% for BRCA2, and 12.9% for BRCA1/2 negative families." (PMID 23216834, 2012). "Among 285 female probands, most were breast cancer patients (98%), and 247 (86.7%), 15 (5.3%), and 23 (8.1%) were noncarriers, BRCA1, and BRCA2 carriers respectively." (PMID 22290208, 2012). "Marco Pierotti (Milan, Italy) reviewed his experience with microarray studies aimed at the molecular classification of BRCAX, familial breast cancers that do not involve the BRCA1 and BRCA2 genes." (PMID 16464241, 2006). "Similar results were described in women with or without breast cancer and BRCA1 or BRCA2 carriers." (PMID 37628558, 2023). "The median age of breast cancer diagnosis was 43, 44, and 46 in BRCA1 carriers, BRCA2 carriers, and noncarriers; the median age of ovarian cancer diagnosis was 51, 54, and 52 in BRCA1, BRCA2 carriers, and noncarriers, respectively." (PMID 35378767, 2022). "The family history was negative for other cases of breast cancer or ovarian cancer, but DNA-testing for the BRCA1 and BRCA2 genes was offered based on a high grade serous ovarian tumour meeting at least the 10% likelihood threshold defined by UK NICE guidelines." (PMID 36068545, 2022). "This places the receptor phenotypes of the MINAS breast cancers intermediate between that of BRCA2 only and BRCA1 only breast cancers, and would be consistent with an independent rather than synergistic effect in BRCA1/BRCA2 MINAS." (PMID 34983940, 2022). "In BRCA1-depleted SUM149 breast cancer cells and PDX models, treatment with an EZH2i and PARPi reduced tumour growth more than single PARPi treatment; however, this effect was not seen in a BRCA2-depleted mouse model of breast cancer." (PMID 35326684, 2022). "Furthermore, HER2-negative breast cancers were significantly more prevalent among BRCA1 (98.2% vs 77.7%, p < 0.001) and BRCA2 (95.0% vs 77.7%, p = 0.001) PV carriers than non-PV carriers." (PMID 35135604, 2022). "Her mother had breast cancer at age 41 and a non-informative BRCA1 and BRCA2 study result." (PMID 34771502, 2021). "For ovarian cancers, although the HRs were of similar magnitude as for breast cancers in BRCA1 and BRCA2 carriers, respectively, the HRs were not significant (BRCA2 carriers, P = 0.10 and BRCA1 carriers, P = 0.11) likely reflecting the smaller number of events." (PMID 32175645, 2020). "– 32-year-old female, BRCA2 PV/LPV carrier, without children, with breast cancer." (PMID 33110458, 2020). "The final version of the kit contained 34 target specific probes, corresponding to the BAC classifier regions, 7 reference probes, randomly spread over the genome and in regions not affected in breast cancer, 2 probes for BRCA1 and 2 probes for BRCA2, resulting in a total of 45 probes." (PMID 22032731, 2011). "Because BRCA1 and BRCA2 expressions are often decreased, or even absent in sporadic breast cancer, abnormal BRCA1 or BRCA2 expressions may also play a role in nonhereditary tumors." (PMID 19442290, 2009).
breast cancer (continued). "Presumably, this discrepancy results from the fact that BRCAPRO does not model any of the residual familial clustering of breast cancer, other than BRCA1 or BRCA2, so that individuals with moderate family histories are assigned probabilities for being mutation carriers that are too high." (PMID 16417652, 2006). "Second primary breast cancers (2.12 v 1.42 events per 100 person-year) and nonbreast primary malignancies (0.70 v 0.45 events per 100 person-year) were more frequent among BRCA1 than BRCA2 carriers, whereas distant recurrences were less frequent (1.51 v 2.06 events per 100 person-year)." (PMID 39993249, 2025).
ovarian carcinoma (1,831 papers, 1995 to 2026). A malignant neoplasm originating from the surface ovarian epithelium. "The ovarian cancer cumulative risk to age 80 years is considerably higher in women with a pathogenic BRCA1 variant compared to those with a pathogenic BRCA2 variant (BRCA1: 44%, BRCA2: 17%)." (PMID 41528496, 2026). "Here we analyzed the 60KJPN dataset for BRCA1/BRCA2 variants and compared them with the previous version, 54KJPN, to ascertain the frequency of hereditary breast and ovarian cancers in the general Japanese population." (PMID 41565638, 2026). "In another study, ctDNA BRCA1 and BRCA2 reversal mutations were detected in 112 ovarian cancer patients treated with PARP inhibitors, with eight patients acquiring reversal mutations." (PMID 41602395, 2026). "Women with a BRCA1 or BRCA2 gene mutation are at increased risk of developing breast and ovarian cancer." (PMID 41025376, 2026). "Interventions that target decisional conflict are needed to increase the uptake of RRSO which will result in a reduction of the risk of ovarian cancer in women with BRCA1 or BRCA2 PV." (PMID 41547865, 2026). "Collectively, our findings establish RAD52 as a promising therapeutic target to overcome PARP inhibitor resistance in BRCA2 -mutated ovarian cancer and offer mechanistic insights to inform future clinical strategies." (PMID 41040355, 2025). "Background/Objectives: Mutations in the BRCA1 and BRCA2 genes are well-known risk factors for ovarian cancer." (PMID 40869932, 2025). "Mutations in pathogenic variants of BRCA1 and BRCA2 are reported to lead to lifetime risks of developing breast and ovarian cancer, as high as 84 and 45%, respectively." (PMID 40361383, 2025). "The identification of pathogenic variants in BRCA1 and BRCA2 is a critical predictive biomarker for the use of PARP inhibitors in women with epithelial ovarian cancer." (PMID 40805236, 2025). "BRCA1 and BRCA2 play an important role in the repair of double-stranded DNA (dsDNA) breaks through homologous recombination, and women with BRCA1 or BRCA2 gene mutations are predisposed to cancers such as breast and ovarian cancer." (PMID 40243501, 2025). "Most studies focus on understanding differences in transcriptome profiles of ovarian cancer patients bearing variants in BRCA1 or BRCA2." (PMID 41463479, 2025). "Inherited pathogenic variants in BRCA2 confer an average cumulative lifetime risk of developing breast and ovarian cancer of about 69% and 17%, respectively." (PMID 40232841, 2025). "Individuals with inherited mutations in BRCA1 or BRCA2 have a significantly higher risk of developing breast and ovarian cancers compared with the general population." (PMID 39996890, 2025). "In particular, women with mutations in BRCA1 (located on chromosome 17q21) or BRCA2 (located on chromosome 13q12.3) have an increased risk of developing breast and ovarian cancer." (PMID 40427158, 2025). "Women with BRCA1 and BRCA2 mutations have a higher risk of developing breast and ovarian cancers, which tend to occur at younger ages." (PMID 41333220, 2025). "Among these genomic alterations, BRCA1 and BRCA2—genes traditionally associated with breast and ovarian cancers—are emerging as key players in OSCC due to their roles in maintaining genomic stability and regulating DNA damage repair." (PMID 40224184, 2025). "Women with BRCA1 mutations have a 35-70% lifetime risk of ovarian cancer, while BRCA2 mutation carriers have a 10-30% risk." (PMID 40303993, 2025). "The majority of these hits were neoplasm-related and were associations between BRCA2 and breast/ovarian cancer, confirming the previous results." (PMID 39799398, 2025). "This study suggests that ovarian carcinomas demonstrate better NACT outcomes in BRCA2- vs. BRCA1-mutated hereditary ovarian carcinomas, probably due to the higher sensitivity of the former to carboplatin-paclitaxel." (PMID 40547808, 2025). "BRCA1 and BRCA2 germline mutations are linked to a high percentage of hereditary breast and ovarian cancers." (PMID 40904409, 2025).
ovarian carcinoma (continued). "Specific genetic mutations in oncogenes, such as BRCA1 and BRCA2, are linked to various cancers, including breast and ovarian cancer." (PMID 41180630, 2025). "Mutations in BRCA1 and BRCA2 genes disrupt these repair mechanisms, predisposing individuals to an elevated risk of breast and ovarian cancers." (PMID 40599862, 2025). "By age 70, women with BRCA1 mutations have a 39% risk of developing ovarian cancer, while those with BRCA2 mutations have an 11% risk." (PMID 41471359, 2025). "An example of this is finding pathogenic variants in the BRCA1/BRCA2 genes which can cause hereditary breast and ovarian cancer and identification directly impacts therapeutic planning for the patient." (PMID 39945861, 2025). "During the later 1990s, biotech startup Myriad had secured patents on the BRCA1 and BRCA2 genes, certain variants of which are associated with significantly elevated risk of breast and ovarian cancer." (PMID 39825701, 2025). "BRCA1 PV carriers had a significantly higher risk of developing second breast or ovarian cancer than BRCA2 or WT carriers (p = 0.010)." (PMID 40422528, 2025). "We tested two PARP inhibitor-resistant Brca2 -deficient mouse ovarian cancer models, ID8-OR and HGS2-OR." (PMID 41040355, 2025). "SNRPB knockdown inhibited ovarian cancer cell proliferation, downregulated DNA replication and HR genes, and promoted aberrant BRCA2 exon 3 skipping, leading to a loss of the PALB2 binding domain and further impairment of HR." (PMID 40724944, 2025). "Germline mutations in BRCA1 and BRCA2 predispose patients to around 40–70% of breast and ovarian cancers, making preventive strategies crucial for these patients." (PMID 40647506, 2025). "BRCA1 and BRCA2 mutations are widely recognised as significant risk factors for hereditary breast and ovarian cancers, accounting for a substantial proportion of these malignancies." (PMID 40949480, 2025). "Carriers of germline BRCA1/BRCA2 pathogenic variants (BRCA PVs) have increased risk of ovarian cancer (OC)." (PMID 40116830, 2025). "The mutations in BRCA1 and BRCA2 genes are reported to increase the risk of ovarian cancer 12-fold and 5-fold, respectively." (PMID 40894326, 2025). "In the early 1990s, both BRCA1 and BRCA2 were identified as cancer susceptibility genes in patients with early-onset breast and ovarian cancer." (PMID 40988318, 2025). "This review explores the role of the BRCA1 and BRCA2 genes—traditionally associated with breast and ovarian cancers—in the context of OSCC." (PMID 40224184, 2025). "Approximately 15% of non-mucinous epithelial ovarian cancer patients carry germline mutations in BRCA1 or BRCA2, and approximately 5–7% of ovarian cancer patients have somatic BRCA mutations." (PMID 40243501, 2025). "Several Latin American countries have published studies on BRCA1 and BRCA2 mutations in breast and ovarian cancer patients, offering valuable insights into regional mutation patterns." (PMID 40710012, 2025). "Carriers of germline pathogenic variants (PVs) in the BRCA1 and BRCA2 genes are at higher risk of developing breast and ovarian cancer than the general population." (PMID 40399999, 2025). "One year later, ovarian cancer was diagnosed, with molecular analysis indicating interstitial heterozygous loss of the BRCA2 gene locus, providing a rationale for targeted therapy with the PARP inhibitor olaparib." (PMID 39820556, 2025). "Mutations in exon 11 of both BRCA1 and BRCA2 have drawn considerable attention because of their potential impact on ovarian cancer outcomes, particularly disease onset and progression." (PMID 40427158, 2025). "Taken together, our study, which integrated clinical, population-based, and computational data, provides a more comprehensive view of the potential functional and clinical impact of BRCA2 variants in Mexican patients with breast and ovarian cancer." (PMID 41283249, 2025).
ovarian carcinoma (continued). "Recent Danish papers on the distribution of gene variants in a 2006–08 cohort of patients with a suspected hereditary predisposition to breast and/or ovarian cancer found that 28% of the highly selected cohort had a pathogenic BRCA1 or BRCA2 variant." (PMID 40507299, 2025). "Germline mutations in canine BRCA1 and BRCA2 have been associated with a higher risk of CMTs, analogously to their role in human breast and ovarian cancers." (PMID 40004231, 2025). "Mutations in the BRCA1 and BRCA2 genes are the most significant genetic factors associated with an increased risk of developing ovarian cancer." (PMID 40664665, 2025). "PARP Inhibitors were approved as first-generation synthetic lethal agents for advanced ovarian cancer with BRCA1 or BRCA2 mutations." (PMID 39885134, 2025). "PALB2 (Partner and Localizer of BRCA2) was first identified as a protein that interacts with breast cancer type 2 susceptibility protein (BRCA2), a well-known tumor suppressor associated with higher breast and ovarian cancer risk." (PMID 39941813, 2025). "The presence of mutations in the BRCA2 gene has been demonstrated to be a significant predictor of an elevated risk of developing breast and ovarian cancers." (PMID 40843725, 2025). "This mutation is located within the ovarian cancer cluster region of BRCA2, which is where half of Japanese patients with ovarian cancer and gBRCA2 mutations were reported to have variants." (PMID 40091949, 2025). "A case–control study further confirmed this finding in Asian, revealing that approximately 15.8% of ovarian cancer patients harbored mutations in the BRCA1 or BRCA2 genes in Pakistani countries." (PMID 40558241, 2025). "Our results indicate that the location of BRCA mutations, particularly within BRCA2 exon 11, is associated with differences in the survival outcomes of patients with ovarian cancer." (PMID 40427158, 2025). "Although differences in response to Olaparib are cell line-dependent, PEO1 cells harbor a nonsense mutation in exon 11 of BRCA2; this genomic feature has been shown to render ovarian cancer patients more sensitive to Olaparib treatment." (PMID 41465250, 2025). "For those with a family history of breast or ovarian cancer, genetic testing for BRCA2 mutations is frequently necessary." (PMID 40141415, 2025). "Targeting GRB2 in combination with PARP inhibitors shows potential for enhancing immune response and reducing tumor burden, particularly in BRCA2-deficient ovarian cancers." (PMID 39949780, 2025). "Mutations in BRCA1 and BRCA2 genes are major contributors to ovarian cancer risk, as these genes play crucial roles in DNA repair through the homologous recombination pathway, ensuring cellular genetic stability." (PMID 40303993, 2025). "Hereditary ovarian carcinomas demonstrate better NACT outcomes in BRCA2 vs. BRCA1 mutation carriers." (PMID 40547808, 2025). "This study aimed to evaluate the progression-free survival (PFS) benefit from the PARP inhibitor in relation to the location of mutations in BRCA1/BRCA2 in newly diagnosed ovarian cancer." (PMID 40075604, 2025). "There was one patient with ovarian cancer harboring an MSH3 variant in addition to the BRCA2 variant, with the former variant also possibly contributing to the phenotype." (PMID 41465149, 2025). "Early identification of mutations in BRCA1 and BRCA2 can have important implications for the diagnosis, treatment, and management of patients at high genetic risk of developing breast and ovarian cancer." (PMID 40071159, 2025). "Women carrying BRCA1 mutations face a 39%-44% lifetime risk, while BRCA2 mutation carriers have an 11%-17% lifetime risk of developing ovarian cancer (American Cancer Society)." (PMID 40664665, 2025).